PNLIP (pancreatic lipase)
Diseases named in the same sentence as PNLIP in open-access papers (continued):
Sharing a sentence is not in itself a finding about the gene and the disease.
Obesity (continued). "Song reported that SB administration alleviated obesity and hypertriglyceridemia in db/db mice, and Matsuo reported that SB decreased pancreatic lipase activity in vitro and decreased serum TG levels in intralipid-fed ddY mice." (PMID 30744038, 2019). "Its effectiveness in inhibiting pancreatic lipase and on adipocyte differentiation has also been frequently reported, thus confirming its therapeutic potential in obesity management." (PMID 30626104, 2019). "Another strategy that has been proposed for the treatment of obesity is to inhibit pancreatic lipase, which consequently decreases lipid absorption in the intestine." (PMID 30626104, 2019). "Digestion of fat is a prerequisite for its uptake and the inhibition of pancreatic lipase, the most important enzyme responsible for the digestion of dietary triglycerides, can be used to manage weight and potentially reduce obesity." (PMID 30781736, 2019). "The anti-obesity properties of natural plant extracts can also be determined by porcine pancreatic lipase (PPL) in vitro activity assay." (PMID 31540021, 2019). "Orlistat, a hydrogenated derivative of lipstatin, is the only pancreatic lipase inhibitor currently approved for a long-term treatment of obesity." (PMID 30026782, 2018). "Orlistat is a clinically available anti-obesity drug that acts as inhibitor of gastric and pancreatic lipase and has been shown to block the absorption of dietary fats of about 30% at the therapeutic oral dosage of 120 mg per three times a day." (PMID 30384448, 2018). "Our results suggest natural resources that possess strong antioxidant and pancreatic lipase inhibitory activities with potential applications in the treatment and prevention of obesity and overweight problem." (PMID 30026782, 2018). "Pancreatic lipase, a key enzyme for lipid absorption, is one of the most important targets for the treatment of obesity, while natural compounds have recently attracted much interest as potential inhibitors of this enzyme." (PMID 30384448, 2018). "Pomegranate leaf extract containing abundant tannins, for example, can hamper the development of obesity and hyperlipidemia in high-fat diet induced obese mice by inhibiting the pancreatic lipase activity and suppressing energy intake." (PMID 30080863, 2018). "Our results suggest natural resources that possess strong antioxidant and pancreatic lipase inhibitory activities with potential applications in the treatment and prevention of obesity and overweight." (PMID 30026782, 2018). "An important target to fight obesity includes the development of inhibitors of pancreatic lipase, a key enzyme in the digestion and absorption of dietary fats." (PMID 30384448, 2018). "Another clinical approach to preventing or treating obesity is through retarding the intestinal absorption of dietary fat by inhibition of pancreatic lipase activity." (PMID 29385084, 2018). "Theaflavis and other tea polyphenols have showed tendency to inhibit the expressions of key obesity related targets like pancreatic lipase (PL) that plays a central role in fat metabolism." (PMID 29592809, 2018). "The ethanol extract of AL exerted an essential inhibitory effect on lipase with the IC50 9.06 μg/mL in a human pancreatic lipase assay, and exhibited anti-obesity effect on a high-fat diet-induced obesity mice model at the high concentration of 500 mg/kg." (PMID 30505341, 2018). "For anti-obesity activities, SE-EA indicated the highest suppression effect on pancreatic lipase (IC50 = 3.67 ± 0.52 mg/mL)." (PMID 29065451, 2017). "Because pancreatic lipase (PL) can decompose 50–70% of fat, developing its inhibitor as an anti-obesity drug is preferred." (PMID 28498356, 2017). "According to the obtained results, V. vinifera, R. coriaria, and O. dayi can be used as natural inhibitors of pancreatic lipase and so are new players in obesity treatment." (PMID 29292744, 2017).
Obesity (continued). "A specific pancreatic lipase inhibitor, orlistat, has been clinically used for the prevention of obesity and many fields of research have focused on developing anti-obesity therapeutics with more efficiency and less side effect." (PMID 28253267, 2017). "No abnormal bowel activities (no oily stools, no diarrhoea) were recorded in the treated group, as it is the case with the commonly prescribed anti-obesity drug, pancreatic lipase inhibitor, Orlistat® at the required dosage of 120 mg, three times a day." (PMID 28814950, 2017). "The suppression of dietary lipid absorption by inhibiting the activity of pancreatic lipase has been a promising strategy for treating obesity." (PMID 29065451, 2017). "For the development of new anti-obesity drugs, especially pancreatic lipase inhibitors, further studies on structure–activity relationships are required to establish new pharmacological leads based on the algal products." (PMID 27941599, 2016). "According to the present study's results, it can be deduced that Aloe vera gel inhibits porcine pancreatic lipase and thus deserves to be further explored as a weight lowering agent to combat obesity." (PMID 26880905, 2016). "Inhibition of lipases, especially pancreatic lipase, is one of the main therapeutic targets of anti-obesity drugs." (PMID 27941599, 2016). "Orlistat, which prevents fat absorption via pancreatic lipase inhibition, is marketed as an anti-obesity agent." (PMID 26938273, 2016). "To date, orlistat (Xenical) approved by FDA, relatively effective drug for long-term treatment of obesity, exerts the drug efficacy through inhibition of pancreatic lipase enzyme and prevents the absorption of approximately 30% of dietary fat." (PMID 27529064, 2016). "Of the phlorotannins, eckol appears to be the most promising target compound for anti-obesity drug development due to its multiple inhibitions on pancreatic lipase, adipogenesis and PTP1B." (PMID 27941599, 2016). "Phlorotannins alleviate obesity and obesity-related disorders through several mechanisms, including inhibition of pancreatic lipase (see Section 3) and obstruction of adipocyte differentiation." (PMID 27941599, 2016). "The anti-obesity effects of the algal compounds, apart from their pancreatic lipase inhibitory activity, are covered in detail in the following sections." (PMID 27941599, 2016). "Bioactive compounds that inhibit gastric and pancreatic lipase activity appear to be the main target in the search for anti-obesity agents." (PMID 27941599, 2016). "Some pharmacological obesity treatments, for example, Orlistat, function through specific, irreversible inhibition of gastrointestinal lipases, of which pancreatic lipase is the most biologically active and important one in healthy humans." (PMID 26880905, 2016). "The technology of using alginates as an inhibitor of pancreatic lipase has been patented, and there is a potential application of the compound as an anti-obesity agent." (PMID 27941599, 2016). "This extract was able to inhibit dietary fat absorption by inhibiting pancreatic lipase activity, and its ability to prevent obesity was also tested in vivo." (PMID 27775618, 2016). "In attempts to identify natural products for overcoming obesity, more researches have been focused on the identification of newer pancreatic lipase inhibitors with less unpleasant adverse effects." (PMID 26640503, 2015). "The reduction of fat absorption through pancreatic lipase inhibition is known to benefit the regulation of obesity." (PMID 26085282, 2015). "The suppression of pancreatic lipase-mediated fat hydrolysis is an effective strategy for prevention of obesity and hyperlipidemia." (PMID 25884980, 2015). "Due to the huge success of natural products for management of obesity, more research has been focused on the identification of newer pancreatic lipase inhibitors with less unpleasant adverse effects." (PMID 26640503, 2015).
Obesity (continued). "Orlistat, a U.S. FDA-approved drug designed for obesity, inhibits pancreatic lipase, thereby preventing the absorption of free FAs from the diet in the intestine." (PMID 25313139, 2014). "Inhibiting pancreatic lipase is an important strategy for treating obesity and other metabolic disorders." (PMID 25280587, 2014). "Much in line with our report, the only anti-obesity drug currently approved in Europe is Orlistat, a PNLIP inhibitor." (PMID 24262094, 2014). "Pancreatic lipase is a major enzyme involved in triglyceride absorption in the intestine, and inhibiting fat absorption from the diet is a target for treating obesity." (PMID 25280587, 2014). "Among these, both natural and synthetic pancreatic lipase inhibitors are effective in obesity prevention, likely due to their inhibition of intestinal lipid absorption." (PMID 24321125, 2013). "In animal studies, a major tea catechin, (−)-epigallocatechin-3-gallate and polyphenol extracts in black tea prevented high-fat diet-induced obesity via the inhibition of pancreatic lipase." (PMID 24321125, 2013). "Orlistat has been a familiar pancreatic lipase inhibitor available in the market as an anti-obesity drug since 1999." (PMID 26784466, 2013). "To begin the search for alternative anti-obesity agents, we exploited a hen immunization model to produce Anti-lipase IgY, a novel antibody that recognizes porcine pancreatic lipase." (PMID 24321125, 2013). "Recently, newer approaches for the treatment of obesity have involved inhibition of dietary triglyceride absorption via inhibition of pancreatic lipase as this is the major source of excess calories." (PMID 24160551, 2013). "Many drugs have been found to treat obesity, such as Orlistat, which is well known as a gastric and pancreatic lipase inhibitor." (PMID 23377020, 2013). "One example is orlistat, a derivative of the naturally occurring potential pancreatic lipase inhibitor produced from Streptomyces toxytricini, which is used clinically in treatment of obesity by reducing the energy intake from the diet." (PMID 24002138, 2013). "Taken together, these results suggest that the anti-obesity effects of POCU1b involve the inhibition of pancreatic lipase activity and adipogenesis via the down-regulation of lipid accumulation." (PMID 24160551, 2013). "Two different types of obesity treatment drugs are currently available in the market, including orlistat, which reduces intestinal fat absorption through inhibition of pancreatic lipase, and sibutramine, which is an anorectic." (PMID 26784466, 2013). "Pancreatic lipase inhibitor has attracted much attention for its key role in obesity treatment due to its effectiveness and low toxicity." (PMID 26784466, 2013). "Inhibition of pancreatic lipase is an attractive targeted approach for the discovery of potent anti-obesity agents for obesity treatment." (PMID 22408418, 2012). "The inhibition of dietary fat absorption is a logical target for managing obesity, and pancreatic lipase is a key enzyme involved in triglyceride absorption in the small intestine." (PMID 23365603, 2012). "It has been clinically reported that a pancreatic lipase inhibitor such as orlistat prevented obesity and hyperlipidemia through the increment of fat excretion into feces and the inhibition of pancreatic lipase." (PMID 23258993, 2012). "The application of pancreatic lipase inhibitor was examined as a treatment for diet-induced obesity in humans." (PMID 23258993, 2012). "In this paper, we screened 115 herbal extracts for inhibition of porcine pancreatic lipase to identify effective herb to treat obesity." (PMID 23365603, 2012). "Regarding anti-obesity drugs, orlistat is a gastric and pancreatic lipase inhibitor that reduces dietary fat absorption." (PMID 22698140, 2012). "To identify effective herb to treat obesity, we screened 115 herbal extracts for inhibition of porcine pancreatic lipase (triacylg-ycerol acylhydrolase, EC 3.1.1.3) activity in vitro." (PMID 23365603, 2012).
Obesity (continued). "Orlistat is a gastric and pancreatic lipase inhibitor used in obesity management, inhibiting the absorption of fat from the diet and causing a high faecal fat content." (PMID 16938137, 2006). "It has been reported that a pancreatic lipase inhibitor, orlistat prevented obesity and hyperlipidemia through the enhancement of fat excretion in feces and the inhibition of pancreatic lipase." (PMID 15811191, 2005). "Therefore, the quest for effective obesity treatments, especially those that target pancreatic lipase for the reduction of fat absorption, reveals both challenges and opportunities." (PMID 40016558, 2025). "However, the excessive release of free fatty acids by pancreatic lipase can lead to elevated fat storage in white adipose tissue, contributing to obesity and related metabolic disorders." (PMID 41011118, 2025). "The moderate inhibition of pancreatic lipase observed suggests a potential role for sodium alginates in obesity management by reducing the breakdown and absorption of dietary triglycerides, potentially limiting lipid accumulation and supporting weight management." (PMID 40076378, 2025). "Obesity can be treated by inhibiting the pancreatic lipase enzyme." (PMID 39852154, 2025). "One treatment for obesity is orlistat, a drug that inhibits pancreatic lipase." (PMID 40509279, 2025). "In addition to in vitro tests with pancreatic lipase, preclinical animal models of obesity have emerged as a significant tool for evaluating the potential effects of extracts and other natural-derived materials." (PMID 40509279, 2025). "Although not as efficient or significant as orlistat and acarbose, ACH effectively inhibited pancreatic lipase, α-amylase, and α-glucosidase within a specific concentration range, providing optimism for its potential use as an anti-obesity and anti-diabetic agent in the future." (PMID 41300115, 2025). "In addition to pancreatic lipase, cholesterol esterase represents another molecular target for the development of novel compounds to combat obesity." (PMID 40509279, 2025). "Therefore, targeting pancreatic lipase to decrease fat digestion and absorption represents a promising strategy to combat obesity." (PMID 41008249, 2025). "Collectively, these diverse research approaches strongly suggest that nutmeg, particularly through THF, holds potential as a natural inhibitor of pancreatic lipase, offering a promising strategy for obesity management by reducing the absorption of dietary fats." (PMID 40016558, 2025). "In contrast to the research conducted with pancreatic lipase or cholesterol esterase, there has been a paucity of studies determining the potential anti-obesity properties of bioactive compounds in combination with orlistat in other biological models or clinical trials." (PMID 40509279, 2025). "Therefore, the inhibition of pancreatic lipase can reduce the intestinal absorption of triglycerides, thereby preventing hyperlipidemia and obesity." (PMID 40137304, 2025). "Among the three drugs for obesity treatment, only orlistat acts by inhibiting pancreatic lipase." (PMID 41300115, 2025). "Pancreatic lipase is the enzyme responsible for the digestion and absorption of triglycerides, and its inhibition is one of the most widely studied methods to determine the potential activity of natural products to prevent and treat obesity." (PMID 41295388, 2025). "Pancreatic lipase, a key enzyme in dietary fat digestion and absorption, exhibits inhibitory effects that reduce lipid hydrolysis and absorption, thereby exerting anti-obesity and lipid-lowering effects." (PMID 41008139, 2025). "Moreover, extracts showed inhibitory activities against porcine pancreatic lipase and α-amylase, with the acidic extract at pH 9 showing the best anti-obesity properties (IC50 = 5.38 ± 0.34 mg.mL−1 for lipase and IC50 = 5.79 ± 0.30 mg.mL−1 for α-amylase)." (PMID 39852537, 2025).
Obesity (continued). "Additionally, other reports suggested that cyanidin and cyanidin-3-O-β-D-glucoside exhibited their anti-obesity potential by inhibiting pancreatic lipase enzyme or stimulating lipoprotein lipase (LPL) activity." (PMID 40368975, 2025). "Therefore, inhibiting the activity of pancreatic lipase can reduce lipid absorption, which in turn reduces obesity." (PMID 41154479, 2025). "Similarly, anti-obesity potential through the inhibition of pancreatic lipase has also been studied for the extract from the leaves and inflorescence of LC." (PMID 38473839, 2024). "Orlistat is a drug used to treat obesity, mainly by inhibiting the activity of pancreatic lipase." (PMID 39796304, 2024). "In comparison to non-transformed shoots, transformed shoot lines exhibited a higher capability for the inhibition of enzymes related to neurodegeneration (acetylcholinesterase and tyrosinase), diabetes (α-amylase), and obesity (pancreatic lipase and cholesterol esterase)." (PMID 39202972, 2024). "Pancreatic lipase inhibition is a promising mechanism to combat obesity and hypertriglyceridemia." (PMID 39507059, 2024). "Additionally, α-Mangostin not only enhances the activity of the lipoprotein lipase enzyme, which facilitates the breakdown of Very Low-Density Lipoprotein (VLDL), but also promotes the secretion of pancreatic lipase and α-amylase in the anti-obesity mechanism." (PMID 39598280, 2024). "Therefore, the creation of pancreatic lipase inhibitors is a crucial goal for the treatment of obesity." (PMID 38397458, 2024). "Therefore, pancreatic lipase inhibition is an investigational mechanism for identifying potential anti-obesity drugs." (PMID 39796304, 2024). "Pancreatic lipase is a critical enzyme involved in the metabolism of lipids, and substances that inhibit its activity could potentially be useful in addressing obesity and hyperlipidemia." (PMID 38254575, 2024). "In this previous work, we described that silibinin interacts with the hydrophobic sites of the catalytic centre of pancreatic lipase in a similar way that orlistat does, which suggests that silibinin has the potential as a complement to dietary therapy for the treatment of obesity." (PMID 39684564, 2024). "Consequently, ongoing research efforts are dedicated to the exploration and development of novel pancreatic lipase inhibitors that possess improved safety profiles and diminished adverse effects for individuals with obesity." (PMID 38298460, 2024). "In addition, MLP can inhibit the expression of pancreatic lipase and reduce the intestinal absorption ability of dietary fat, thus playing an anti-obesity role." (PMID 38672381, 2024). "Inhibiting pancreatic lipase directly affects lipid metabolism by limiting the breakdown of dietary fats, leading to a decrease in the absorption of triglycerides, which is crucial in treating obesity and dyslipidemia." (PMID 38794679, 2024). "Therefore, it is necessary to find novel, effective, and safe pancreatic lipase inhibitors among natural products for use in the alleviation of obesity." (PMID 39125445, 2024). "However, we recently identified silibinin, the main bioactive compound of thistle extract, as an in vitro pancreatic lipase inhibitor, which suggested a potential role as an anti-obesity agent." (PMID 39684564, 2024). "Inhibition of pancreatic lipase by inhibitors such as orlistat is a principal therapeutic mechanism for suppressing the digestion of dietary triacylglycerols (lipolysis) and a strategy for treating obesity and hyperlipidemia." (PMID 39065479, 2024). "Moreover, studies emphasized the antiobesity and antioxidant potentials of selected medicinal plants and plant extracts, showcasing their ability to inhibit pancreatic lipase and suggesting their application in managing obesity and related conditions." (PMID 39195481, 2024).